NUDT5 (nudix hydrolase 5)
Diseases named in the same sentence as NUDT5 in open-access papers (continued):
Sharing a sentence is not in itself a finding about the gene and the disease.
breast carcinoma (continued). "Nudix hydrolase 5 (NUDT5), crucial for ATP synthesis in breast cancer cell nuclei, is targeted by TH5427, a specific inhibitor that disrupts nuclear ATP generation, impacting hormone-induced chromatin remodeling and progestin-dependent gene regulation." (PMID 38481812, 2024). "NUDIX hydrolase type 5 (NUDT5, also called NUDIX5) is a significant target for the development of breast cancer drugs." (PMID 36177227, 2022). "The interactions with active site amino acids of ribosyltransferase (code: 3GEY) and NUDT5 (PDB code : 5NWH) of interest in treating bacterial infection and breast cancer, respectively, involved the hydrogen bond formation and arene-cation interaction." (PMID 38435083, 2022). "However, the role of NUDT5 in breast cancer remains unknown." (PMID 33571243, 2021). "Thus, NUDT5 may be a novel prognostic factor and potential therapeutic target in breast cancer." (PMID 33571243, 2021). "With the overexpression of NUDT5, tumor-relevant proteins MUC1 which was known to upregulate the EMT drivers’ expression, was also enriched in breast cancer cell." (PMID 32518727, 2020). "Collectively, these experiments confirm NUDT5 as an integral factor in progestin signaling and that TH5427 is a potent NUDT5 inhibitor that blocks hormone-dependent gene expression in breast cancer cells." (PMID 29343827, 2018). "Breast carcinoma is closely related to some gene products such as Helix Pomatia Agglutinin (HPA), Maternal Embryonic Leucine Zipper Kinase (MELK), Human Protein Kinase 2 alpha (CK2a), and NUDIX hydrolase 5 (NUDT5)." (PMID 41237100, 2025). "NUDT1, NUDT2, NUDT5, and NUDT16 were overexpressed in breast cancer tissue." (PMID 40839607, 2025). "More studies now focus on the identification of NUDT5 inhibitors from approved drugs and small molecules, and a potent TH5427 was tested and shown to block hormone signaling and disrupt the proliferation of breast cancer cells." (PMID 36634566, 2023). "Using tissue microarrays from breast cancer samples, staining with this antibody correlates with clinical bad prognosis and metastasis, indicating its possible value as a selection assay for treatment of these patients with inhibitors of PARP or NUDT5." (PMID 33668737, 2021). "Nevertheless, the role of NUDT5 in breast cancer progression and prognosis has not yet been systematically studied." (PMID 33571243, 2021). "Furthermore, when extracting the co-expression gene list from TCGA and METABRIC datasets, we observed that LSM2 was closely co-expressed with various breast cancer biomarkers such as PDCD5 and NUDT5." (PMID 34638387, 2021). "To further explore NUDT5 biology, we develop targeted NUDT5 inhibitors via a cellular thermal shift assay (CETSA)-guided screening funnel and utilize these compounds to study the role of NUDT5 in progestin-stimulated breast cancer cells." (PMID 29343827, 2018). "In addition, NUDT5 was recently shown to be responsible for the production of PAR-mediated nuclear ATP and, thus, subsequent ATP-dependent chromatin remodeling and gene regulation following progestin or estrogen stimulation in breast cancer cells." (PMID 29343827, 2018). "However, the relationship between NUDT5 and breast cancer have not yet been thoroughly studied." (PMID 33571243, 2021).
colorectal cancer (2 papers, 2017 to 2021). A primary or metastatic malignant neoplasm that affects the colon or rectum. "The present study systematically investigated the expression of MTH1, MTH2, MTH3 and NUDT5 in human colorectal cancer to establish its clinical significance." (PMID 29285286, 2017). "We previously showed that NUDT5 knockdown leads to cell cycle arrest in HeLa cells and apoptosis in the IMR-90 cell line, and high NUDT5 expression is significantly correlated with the occurrence of colorectal cancer and its prognosis." (PMID 33571243, 2021).
lymph node metastasis (2 papers, 2020 to 2021). "In CRC, the levels of MTH1 and NUDT5 were significantly higher in CRC tissues from patients with an advanced AJCC stage and lymph node metastasis and were associated with an extremely poor OS after surgical resection." (PMID 32518727, 2020).
prostate carcinoma (2 papers, 2023 to 2024). A carcinoma that arises from epithelial cells of the prostate gland. "In our study, we show that the methylation level of NUDT5 has a strong causal effect on prostate cancer." (PMID 36634566, 2023). "Furthermore, an increase of 1 SD of NUDT5 methylation was associated with 4% lower risk of prostate cancer (OR: 0.96, 95% CI: 0.95–0.98, PSMR = 1.15 × 10−5)." (PMID 36634566, 2023).
acute lymphoblastic leukemia (1 paper, 2025). Leukemia with an acute onset, characterized by the presence of lymphoblasts in the bone marrow and the peripheral blood. "Finally, we comprehensively identified germline genetic variants in NUDT5 associated with thiopurine-induced myelosuppression in 582 children with acute lymphoblastic leukemia." (PMID 40662362, 2025).
adrenocortical carcinoma (1 paper, 2024). "In adrenocortical carcinoma (ACC), a novel m7G risk signature consisted of METTL1, NCBP1, NUDT1 and NUDT5 was constructed, and the risk score presented significant correlation with enrichment of glycolysis." (PMID 38531882, 2024).
breast tumor (1 paper, 2021). "Our data indicated that NUDT5 overexpressed in breast tumors." (PMID 33571243, 2021).
colorectal tumor (1 paper, 2021). "NUDT5 also significantly correlate with nucleotide metabolism and colorectal tumor." (PMID 33571243, 2021).
endometrial carcinoma (1 paper, 2025). A malignant tumor arising from the epithelium that lines the cavity of the uterine body. "In conclusion, our study demonstrated that NUDT5 is a potential oncogene and prognostic biomarker in endometrial carcinoma." (PMID 40426963, 2025). "In the present study, we investigated the clinical relevance and biological function of NUDT5 in endometrial carcinoma (EC)." (PMID 40426963, 2025). "We further analyzed the expression of NUDT5 in endometrial cancer (EC) cell lines and our tissue microarrays." (PMID 40426963, 2025).
glioblastoma (1 paper, 2022). The most malignant astrocytic tumor (WHO grade IV). "Eight genes associated with glioblastoma prognosis were identified based on LASSO analysis: RPS10, RPS11, RPS19, RSL24D1, RPL39L, EIF3E, NUDT5, and RPF1." (PMID 36733371, 2022). "As can be seen in the figure, two genes, RPL39L and NUDT5, were significant in both univariate and multivariate Cox regression; therefore, these two genes can be considered independent prognostic factors of glioblastoma." (PMID 36733371, 2022). "The expression of RPL39L and NUDT5 in glioblastoma cells and normal cells was detected using qRT-PCR." (PMID 36733371, 2022). "Both RPL39L and NUDT5 were highly expressed in glioblastoma cells." (PMID 36733371, 2022). "Finally, univariate cox and multivariate cox analyses were performed, which identified RPL39L and NUDT5 as independent prognostic factors for glioblastoma." (PMID 36733371, 2022). "Eight genes—RPS10, RPS11, RPS19, RSL24D1, RPL39L, EIF3E, NUDT5, and RPF—were found to have an expression in the prognosis of glioblastoma." (PMID 36733371, 2022). "Two independent prognostic factors in glioblastoma, RPL39L and NUDT5, were identified." (PMID 36733371, 2022). "No studies have been conducted on NUDT5 related to glioblastoma." (PMID 36733371, 2022).
leukemia (1 paper, 2025). A malignant (clonal) hematologic disorder, involving hematopoietic stem cells and characterized by the presence of primitive or atypical myeloid or lymphoid cells in the bone marrow and the blood. "By performing a NUDIX-targeted CRISPR/Cas9 screen in leukemia cells, we identified NUDT5, whose depletion led to drastic thiopurine resistance." (PMID 40662362, 2025). "However, when we queried whole-genome or whole-exome sequencing data on 2,754 ALL cases, we found no NUDT5 mutations in leukemia genomes." (PMID 40662362, 2025).
renal cell carcinoma (1 paper, 2025). "Kaplan–Meier survival analysis showed that elevated NUDT5 expression was associated with poorer survival outcomes in EC and renal cell carcinoma patients." (PMID 40426963, 2025).
type 2 diabetes (1 paper, 2023). "The rs4750175 (NUDT5 methylation associated) was also associated with endocrine-related traits (risk of type 2 diabetes)." (PMID 36634566, 2023).
cancer (23 papers, 2017 to 2025). A tumor composed of atypical neoplastic, often pleomorphic cells that invade other tissues. "Tissue microarray analysis revealed a significant association between high NUDT5 expression and higher histological grades of EC, consistent with findings from public data analysis and earlier clinical studies in other cancers." (PMID 40426963, 2025). "Metastasis and cancer cell motility are also correlated with phenotypic and genomic changes caused by the NUDT5 (Nucleotide Diphosphate Hydrolase Type 5) enzyme that is commonly overexpressed in BC and is associated with a more aggressive cancer phenotype." (PMID 35205770, 2022). "Overexpression of the NUDT5 gene in breast and other cancer types is associated with poor prognosis, increased risk of recurrence and metastasis." (PMID 31510016, 2019). "MTH1 and NUDT5 were reported to be associated with biological malignancy in various cancers." (PMID 32518727, 2020). "Given its role in maintaining NAD+ levels, NUDT5 has emerged as a potential therapeutic target in cancer treatment and there is considerable interest in identifying inhibitors of NUDT5." (PMID 39225905, 2025). "The results revealed that NUDT5 was significantly overexpressed at both mRNA and protein levels in multiple cancers, including EC." (PMID 40426963, 2025). "As a result, NUDT5 was identified and further highlighted as a gene potentially involved in cancer development, based on Open Targets analysis." (PMID 40426963, 2025). "In this regard, the discovery of NUDT5 inhibitors has emerged as a potential therapeutic approach in cancer treatment." (PMID 39225905, 2025). "Three unrelated protein targets linked to cancer or inflammation (SMYD3, NUDT5, and PHIP) were selected." (PMID 39966348, 2025). "The inhibition of NUDT5 enzymatic activities hinders the formation of oncospheres and prevents the activation of cancer-driver genes." (PMID 41009411, 2025). "Due to its significant contribution to pathogenesis, NUDT5 appears to be a promising target for cancer therapy, making the identification of NUDT5 inhibitors crucial for potential treatment advances." (PMID 41009411, 2025). "NUDT5 is differentially expressed in different types of cancer and positively correlated with aggressive cancer disease phenotype, knockdown of which can suppress the proliferation of cancer cells without inducing DNA oxidative lesion." (PMID 36634566, 2023). "Previous researches showed that NUDT5 was significantly correlated with nucleotide metabolism and cancer." (PMID 33571243, 2021). "Another NUDIX hydrolases NUDT5 was also considered to be involved in cancer due to its 8-OH-(d)GDP hydrolysis activity." (PMID 32300600, 2020). "Taken together, these findings indicate that the expression of MTH1 and NUDT5 is correlated with an advanced cancer stage, tumor invasion and a poor prognosis." (PMID 32518727, 2020). "It is known that NUDT5 is an upstream regulator oftumor drivers and are a biomarker for cancer stratification, as well as a target for drugdiscovery towards the treatment of aggressive cancer types and metastasis." (PMID 31902977, 2019). "In this article, we focus on identifying NUDT5-dependent pathways in cancer progression and metastasis." (PMID 31510016, 2019). "Design and development of potential inhibitors to NUDT5 is of interest in the treatment ofbreast cancer." (PMID 31902977, 2019). "The work presented here shed light onto the mechanism by which elevated levels of NUDT5 observed in cancer patients is predictive of a poor outcome and prognosis." (PMID 31510016, 2019). "Inhibiting the enzymatic activities of NUDT5 prevents oncosphere formation and precludes the activation of cancer driver genes." (PMID 31510016, 2019). "NUDT5 functions as a master regulator of key oncogenic pathways and of genes involved in cell adhesion, cancer stem cell (CSC) maintenance and epithelial to mesenchyme transition (EMT)." (PMID 31510016, 2019).
cancer (continued). "Ongoing efforts are aimed at formulating NUDT5 inhibitors for in vivo use and will focus on further investigating the role of NUDT5 in cancer and other disease models." (PMID 29343827, 2018). "We confirm previously known cell cycle perturbations upon NUDIX depletion such as NUDT2 and NUDT5 in cancer cells, characterized by an accumulation in G1 (2 N) phase." (PMID 29142246, 2017). "Recent studies suggest that NUDT5 might facilitate cancer cell survival by maintaining high levels of nucleotide pools, which help cells cope with increased replication stress and DNA damage." (PMID 40426963, 2025). "Expanding the scope of this work to include other cancer types that rely on NUDT5 activity may broaden the potential impact of these findings." (PMID 41009411, 2025). "Next, NUDT5 expression across pan-cancer and normal tissues was examined." (PMID 40426963, 2025). "The relationship between NUDT5 and nucleotide metabolism in cancer is particularly noteworthy." (PMID 38594466, 2024). "NUDT5, an ADP ribose pyrophosphatase, is associated with nucleotide metabolism and cancer." (PMID 38553479, 2024). "MTH1 and NUDT5 belong to clusters that are highly expressed in cancer." (PMID 32518727, 2020). "Taken together, these findings suggest that an elevated level of NUDT5 expression may promote cancer progression in several ways." (PMID 29285286, 2017). "Thus, NUDT5 inhibitors hold promise as a potential treatment approach for tumors with high oxidative stress, such as TNBCs, either as single agent treatments or in combination with other anti-cancer therapies." (PMID 38317231, 2024). "In addition, we identified signaling networks involved in the processes of EMT, cell adhesion, and angiogenesis, which is consistent with our hypothesis and previous work and with the role of NUDT5 in aggressive cancer progression." (PMID 33668737, 2021). "Maybe it’s a potential mechanism of which NUDT5 affect the cancer cell cycle." (PMID 32518727, 2020). "It has been shown that NUDT5 activity can also influence NAD+ homeostasis, thereby affecting cancer cell metabolism and survival." (PMID 39225905, 2025). "NUDT5 (NUDIX hydrolase 5, or NUDIX5), like MTH1, has been connected to the critical nucleotide metabolism and cancer pathways." (PMID 36615284, 2022). "NUDT1, NUDT5, and NUDT14 are highly expressed in cancers, indicating a potential role of these NUDIX enzymes in cancer." (PMID 35168561, 2022). "In this review, we discuss the role of NUDT5 and other members of the NUDT family of enzymes in breast and other cancer types." (PMID 33668737, 2021). "We were curious as to the potential relationship between elevated MTH2, MTH3 and NUDT5 expression in CRC tissues and cancer progression." (PMID 29285286, 2017). "NUDT1, NUDT5, and NUDT14 belong to the cluster of highly expressed NUDIX in cancer, pointing toward a potential role of these NUDIX enzymes in cancer, which has been previously proposed." (PMID 29142246, 2017). "After validation and formulation, successful candidates will then progress to in vivo studies to evaluate their anti-cancer effects and ultimately into clinical trials to confirm or reject the potential for developing a new generation of drugs for BRCA treatment—NUDT5 inhibitors." (PMID 41009411, 2025). "However, a distinct cluster appeared when comparing cancer vs normal tissues, which contained NUDT1, NUDT5, NUDT8, NUDT14, and NUDT22, confirming a potential role of these NUDIX hydrolases in cancer." (PMID 29142246, 2017).
cancer (continued). "Cancer cells often exhibit altered NAD+ metabolism to support their rapid proliferation and survival under stress conditions and it has been shown that modulation of the NUDT5 activity influences NAD+ homeostasis, thereby affecting cancer cell metabolism and survival." (PMID 39225905, 2025). "However, the mechanism by which NUDT5 drives cancer progression and is exploited by cancer cells is not known." (PMID 31510016, 2019). "However, despite the fact that MTH1 and NUDT5 are highly expressed in multiple types of human cancers, the clinical importance of MTH1 and NUDT5 in ESCC tissues and the effects of MTH1 and NUDT5 on ESCC cell growth, invasion and metastasis remain unknown." (PMID 32518727, 2020). "Utilizing RNA-seq data from the Cancer Cell Line Encyclopedia, we found that TNBC cell lines express more NUDT5 mRNA than non-TNBC cell lines." (PMID 38317231, 2024).